RAD51 (RAD51 recombinase)
Diseases named in the same sentence as RAD51 in open-access papers (continued):
Sharing a sentence is not in itself a finding about the gene and the disease.
cancer (568 papers, 2004 to 2026). A tumor composed of atypical neoplastic, often pleomorphic cells that invade other tissues. "Given the central role of RAD51 in protecting against chromosomal instability it stands to reason that RAD51 mutations that alter its function should register in cancer cells." (PMID 42133623, 2026). "Overexpression of RAD51 in various cancers is associated with enhanced DNA repair capacity and resistance to radiation and chemotherapy." (PMID 41190241, 2025). "RAD51 was significantly overexpressed across multiple cancers, including OSCC, and exhibited high diagnostic accuracy for OSCC (AUC = 0.956)." (PMID 41350246, 2025). "In other solid tumors, BRCA1/2, PALB2, or RAD51-mutated cancers have demonstrated sensitivity to platinum-based chemotherapy and PARP inhibition, supporting the rationale for evaluating similar approaches in pNENs." (PMID 41294693, 2025). "RAD51 is involved in the repair of DNA double-strand breaks, and its overexpression has been linked to resistance to radiation therapy in several cancers." (PMID 40869429, 2025). "RAD51 recombinase (RAD51), a central DNA repair protein, plays a crucial role in homologous recombination and has been implicated in cancer progression through mechanisms such as genomic instability, chemoresistance and immune modulation." (PMID 41350246, 2025). "Mechanistically, we demonstrate that FTO inhibition enhanced HNSCC cancer cell radiation response, which was associated with increased DNA damage, reduced homology directed DNA repair efficiency, and reduced RAD51 foci formation." (PMID 40485587, 2025). "ATM-deficient cancer cells rely heavily on RAD51-mediated HR because DSB signaling is weakened, and CHK1-deficient cells similarly depend on RAD51 due to impaired checkpoints." (PMID 41190241, 2025). "This modulation of RAD51 splicing allows cancer cells to better repair the DNA damage caused by oxaliplatin, thus promoting resistance." (PMID 40781643, 2025). "The RAD51 prognostic marker detected 93% (76–99%, 95% CI) of tBRCA1/2-mutated cancer and 45% (34–56%, 95% CI) of the non-tBRCA1/2 mutants with active HRD." (PMID 38397209, 2024). "Failures to properly assemble or regulate RAD51 represent serious implications for genome stability problems and have been associated with the development of various cancers and Fanconi aneamia." (PMID 39268578, 2024). "This multifaceted role highlights the significance of RAD51 in genome maintenance and is further underlined by its mutations associated with cancer and Fanconi anaemia, a rare human disorder linked to defective replication-coupled repair." (PMID 39268578, 2024). "Consistent with this idea, it has been previously shown that the pharmaceutical stabilisation of RAD51 can cause lethality in some cancer cells expressing high levels of the recombinase." (PMID 37239121, 2023). "In the literature, high expression of Rad51 protein is related to genome instability, which is a hallmark of cancer." (PMID 37655260, 2023). "Our experimental system will be valuable for defining the impact of cancer-associated mutations in the RAD51 paralogs on replication fork protection and maintenance." (PMID 37843130, 2023). "For instance, an increased RAD51 foci formation is commonly observed in mutBRCA cancers and its overexpression is associated with PARPi resistance in breast cancer cells." (PMID 38136266, 2023). "Like other homology-directed repair factors, FAAP20 loss causes a reduction in nuclear RAD51 Irradiation-induced foci; and sensitizes cancer cells to ionizing radiation and PARP inhibition." (PMID 37620397, 2023). "Rad51 is essential for the survival of higher eukaryotes and has been implicated in carcinogenesis and cancer progression." (PMID 38003280, 2023). "The common pathway of DNA damage sensing and cell replication control is shared with other proteins, such as BRCA1, PLAB2, BRCA2, and RAD51, whose genes are implied in cancer susceptibility conditions." (PMID 37509701, 2023).
cancer (continued). "Possible gene-gene and gene-environment interactions between Rad51 gene polymorphism and cancer susceptibility need to be further studied." (PMID 36761956, 2023). "RAD51 and paralog defects are associated with both cancer and chemotherapeutic sensitivity, including to PARP inhibitors (PARPi)." (PMID 37488098, 2023). "Mapping of cancer patient mutations as a functional guide confirms ATP-binding matching RAD51 recombinase, yet highlights distinct CX3 interfaces." (PMID 37488098, 2023). "RAD51 and its paralogs are heavily associated with tumorigenesis, as RAD51 tends to be downregulated in many cancers, causing a notable decline in DNA repair capacity, as well as overexpressed in others." (PMID 38001574, 2023). "Overall, our cell line data strongly support the notion that resistance to treatment and particularly to olaparib in BRCA1-deficient cancer cells is frequently associated with restoration of RAD51 foci formation, thus, signing for restored HR capacity." (PMID 37007122, 2023). "The analysis revealed that tumors with high RAD51 mRNA expression is significantly associated with poor outcome in both cancer types." (PMID 35646698, 2022). "According to the literature, RAD51 rs1801320 was also associated with increased risk for breast and other cancers, especially in carriers of BRCA2 mutations." (PMID 36139526, 2022). "This consequence follows from enhanced repair of genotoxic therapy-induced DNA damage by Rad51 elevation which prevents damage-caused cancer cell death." (PMID 35220392, 2022). "RAD51 was overexpressed in 28 types of cancers and was associated with worse overall survival in 11 cancer types." (PMID 35359409, 2022). "KM plot and log-rank analysis of high (50-100%) and low (0-50%) RAD51 patients of significant cancer types in Cox regression were also used to further observe the association of RAD51 and the overall survival of patients." (PMID 35359409, 2022). "Loss of RAD51 function result in an elevated mutation rate and accumulation of DNA damage therefore increase risk of cancer in human." (PMID 35012446, 2022). "Rad51 overexpression is widely detected in human cancers and closely associated with therapy resistance and poor prognosis." (PMID 35220392, 2022). "For microenvironmental scores, RAD51 was negatively associated with the scores in 14 cancer types, while in 3 cancer types, RAD51 was positively associated with the microenvironmental scores." (PMID 35359409, 2022). "RAD51 was associated with cancer stemness, tumor mutational burden, and multiple immunomodulators in different cancer types." (PMID 35359409, 2022). "On the other, RAD51 can be used as a prognostic biomarker for certain cancer types as the expression of RAD51 was found associated with patients’ survival." (PMID 35359409, 2022). "RAD51 is highly expressed in a large proportion of cancers, enhanced RAD51 expression is associated with a poor prognosis and reduced response to treatment." (PMID 36277962, 2022). "RAD51 is implicated in the resistance of cancer cells to PARP inhibitors, therefore representing a perspective target for anticancer therapies." (PMID 36232958, 2022). "Nevertheless, the striking finding of these results was the association of T cells and RAD51 in cancers, which was consistent with previous studies." (PMID 35359409, 2022). "The mutations of RAD51 that have been identified thus far in cancers are mostly coupled to altered DNA binding capacities." (PMID 35137208, 2022). "On one hand, the present study demonstrated that RAD51 has good diagnostic power for multiple cancer types because RAD51 was overexpressed in these cancer types compared to normal tissues." (PMID 35359409, 2022). "In a meta-analysis study on the relationship between RAD51/G135C and cancer risk, Zhao and cowokers (2014) investigated 42 studies involving 19,142 cases and 20,363 controls." (PMID 33778923, 2021).
cancer (continued). "The strong association of RAD51 mRNA with BLM mRNA was seen in eight of the eight most common cancers: breast, lung, acute myeloid leukemia, colon, kidney, thyroid, bladder, and prostate." (PMID 34571923, 2021). "In human cells, RECQ5 depletion causes genomic instability, and RECQ5knockout mice display chromosomal instability, elevated RAD51 foci and cancer predisposition." (PMID 33332547, 2021). "It is worth noting that our results of olaparib resistance in different BRCA1 mutant cells due to EMI1 downregulation that were associated with high RAD51 levels are in line with previous results done either in BRCA1 mutant cancer cells or BRCA2 mutant ones." (PMID 33412559, 2021). "Taken together, these data highlight the fact that RAD51 differs from its HR partners with regard to cancer susceptibility and expose what we call the ‘RAD51 paradox’." (PMID 34316706, 2021). "Cyclin D1, best known for driving cell cycle from G1 to S phase, is also involved in DNA damage repair in association with Rad51, and its inhibition impairs DNA repair capacity leading to sensitization of cancer cells to cisplatin." (PMID 33530952, 2021). "Cyclin D1 is overexpressed in several human cancers, and loss of cyclin D1 reduces damage-induced RAD51 focus formation, impairs HR repair, and sensitizes cancer cells to chemotherapeutic agents." (PMID 34440403, 2021). "The C1ORF112 gene initially drew attention when it was found to be strongly co‐expressed with several genes previously associated with cancer and implicated in DNA repair and cell cycle regulation, such as RAD51 and the BRCA genes." (PMID 33625522, 2021). "While many cancer-related mutations affect HR genes, only two germline mutations in RAD51 have been identified, and their impact on cancer risk remains to be established." (PMID 34316706, 2021). "Expression levels of the RAD51 gene were also significantly associated with the prognosis of patients in some cancers." (PMID 34067336, 2021). "In short, it has been found that autophagy regulates RAD51 protein, but the precise molecular mechanisms underlying how RAD51 regulates autophagy in cancers are still elusive." (PMID 34067336, 2021). "RAD51 overexpression is commonly observed in various types of cancers, that leads to elevated HR efficiency and associated resistance to anti-cancer therapies." (PMID 34576930, 2021). "Conversely, RAD51 is often upregulated in multiple cancer types and is associated with poor survival." (PMID 33709473, 2021). "Ultimately, loss of this complement of functions likely underpins the profound genome stability defects and accumulation of mutations associated with defects in RAD51 and its paralogs, including in cancer cells." (PMID 34545070, 2021). "By exploring cBioPortal, we retrieved the mutation profile of RAD51 in individual TCGA cancer and in a collection of TCGA cancers." (PMID 33952262, 2021). "Most importantly, our second differential hit RAD51 is associated with the NuRD complex and has recently been described to be necessary for the maintenance of active enhancers in different cancer cell lines." (PMID 34359703, 2021). "RAD51 is elevated in many types of cancers, and overexpression of RAD51 has been linked to therapy resistance." (PMID 34716319, 2021). "While loss or reduction of RAD51 protein function can increase cancer risk, RAD51 upregulation in cancer can also contribute to therapeutic resistance." (PMID 33015624, 2020). "Misregulation of RAD51, or one of its regulators, is associated with cancer as well as Fanconi anemia (FA)-like syndrome." (PMID 33015624, 2020). "They showed that EVs effectively delivered siRNAs against RAD51 into target cells, causing selective gene silencing and leading to reproductive cancer cell death by knockdown of RAD51." (PMID 32585976, 2020). "Cancers with deficient RAD51 foci formation (n = 12, p = 0.033, Mann–Whitney) and HRDetect+ve cancers had greater ctDNA suppression (n = 15, p = 0.027, Mann–Whitney)." (PMID 32471999, 2020).
cancer (continued). "Underscoring the importance of tightly controlling RAD51 activity, upregulation or downregulation is associated with genome instability and cancer." (PMID 33015624, 2020). "In this review, we will focus on how misregulation of RAD51, both upregulation and downregulation, results in FA-like syndrome and cancer predisposition." (PMID 33015624, 2020). "Although over 90 cancer- and FA-associated missense variants in RAD51 have been identified, only a handful of these mutations have been functionally characterized." (PMID 33015624, 2020). "Recent huge meta-analyses involving several tens of thousands of subjects provided solid evidence that the variant rs1801320 (135G/C; RC) 135C Rad51 allele localized in the 5’UTR the gene increases the overall risk of cancer." (PMID 31905201, 2020). "Most cancer association studies involving Rad51 were focused on two single nucleotide polymorphisms (SNPs) localized in the 5′ untranslated region (5’UTR) of exon 1 of the gene: rs1801320 (c.−98G>C; 135G/C) and rs1801321 (c.−61G>T; 172G/T)." (PMID 31905201, 2020). "These exosomes effectively delivered siRNA into the recipient cancer cells and caused strong RAD51 knockdown, providing additional evidence of the ability to use human exosomes as vectors in cancer therapy." (PMID 33396739, 2020). "Cancers with HRDetect mutational signatures of HR deficiency had a functional defect in HR, assessed by impaired RAD51 foci formation on end of treatment biopsy." (PMID 32471999, 2020). "BRCA2 interacts with the RAD51 protein, which catalyzes homologous DNA pairing and DNA strand exchange, and overexpression of BRCA2 and RAD51 is associated with poor prognosis in human cancer." (PMID 32005245, 2020). "Cancers with RAD51 foci deficiency had significantly higher HRDetect scores than tumour samples that were RAD51 foci proficient (n = 18, p = 0.0146 Mann–Whitney test)." (PMID 32471999, 2020). "The very few studies analyzing possible cancer risk-modifying effects of Rad51 and/or Xrcc3 haplotypes are, unfortunately, related to different type of cancers." (PMID 31905201, 2020). "Mutations in RAD51 and its regulators are strongly associated with genome instability and cancer predisposition." (PMID 33015624, 2020). "Recently, mutations in the classical RAD51 paralog genes have been linked to predisposition to breast, ovarian or other cancers." (PMID 31584931, 2019). "Secondly, this is the first study not only to assess the correlation between RAD51 SNPs and two associated cancers (HNC and EC) but also to discover a relationship between the rs1801320 polymorphism and the risk of EC." (PMID 31886162, 2019). "This meta-analysis was conducted to evaluate the correlation between the RAD51 polymorphisms and these two cancers quantitatively." (PMID 31886162, 2019). "Currently, there is a critical need to understand the function of the wild-type RAD51 paralogs and determine how their mutations contribute to cancer predisposition." (PMID 30551670, 2018). "The product of the breast cancer–associated gene 2 (BRCA2) acts as a molecular scaffold (mediator) in this process by chaperoning RAD51 onto replication protein A (RPA)-coated ssDNA3." (PMID 30271574, 2018). "Cancer cells harbouring BRCA mutations are unable to recruit RAD51 to dsDNA break sites during HR, thus forcing cells into the more error-prone NHEJ repair pathway." (PMID 29641431, 2018). "Specifically, the RAD51 mediators and their interaction partners are heavily correlated to diseases defined by genomic instability that predispose individuals to cancer." (PMID 30551670, 2018). "Genome analysis of patients with cancer has revealed RAD51 somatic mutations with interesting functional implications." (PMID 30271574, 2018).
cancer (continued). "A single nucleotide polymorphism of RAD51 has also been linked to an elevated risk of a number of cancer types, especially amongst Caucasians29." (PMID 30258062, 2018). "While patients with biallelic mutations in RAD51 and its mediators have been identified in FA patients, monoallelic germline mutations in RAD51 mediators are correlated to predisposition to cancer." (PMID 30551670, 2018). "BRCA2 is a well-known cancer susceptibility gene involved in the repair of double-stranded DNA breaks which functions by regulating the intracellular shuttling and activity of RAD51, another critical protein in homologous recombination." (PMID 28418854, 2017). "While the cause of Rad51 overexpression is still unclear, high Rad51 levels have been proposed as a leading cause of chromosome aberrations in cancer cells." (PMID 28000382, 2017). "Rad51 overexpression is associated with poor prognosis for many cancers, with only two studies showing the opposite relationship." (PMID 27074032, 2016). "Deeper understanding of how 3′UTR variants influence RAD51 activity will pave the way to targeting of the RAD51 pathway as a cancer treatment." (PMID 27733989, 2016). "While disease-associated mutations in RAD51 are extremely rare, depletion by siRNA or miRNA induces a “BRCAness” phenotype and sensitizes cancer cells to DNA damaging agents such as cisplatin and PARP1 inhibitors similarly, to BRCA1 and BRCA2 mutations." (PMID 26910887, 2016). "Naturally occurring single nucleotide polymorphisms (SNPs) of RAD51 have been identified in the population in association with cancer." (PMID 27513445, 2016). "CCDC6 loss or low expression in different cancer models impairs RAD51 foci formation, limits γH2AX foci formation by modulating the activity of the histone phosphatase PP4C and sensitizes the cancer cells to PARPi treatment." (PMID 27884198, 2016). "Therapies targeting Rad51 have been used to inhibit tumor growth and sensitize cancer cells to chemotherapies, and Rad51-based therapy is likely to be associated with very low toxicity." (PMID 27525019, 2016). "Variants of microRNA (miRNA)-binding sites in RAD51 gene’s 3′ untranslated region (3′UTR) are significantly associated with cancer risk, but the roles of these genetic variants in post-transcriptional regulation have not been elucidated." (PMID 27733989, 2016). "Mutation of G to C at position 135 increases the promoter activity of RAD51 thereby elevating RAD51 expression levels, one possible mechanism underpinning the contribution of this mutation to cancer susceptibility." (PMID 27513445, 2016). "A variety of molecular epidemiological studies have been conducted to estimate the association between the RAD51 135G/C polymorphism and risk of cancers." (PMID 27733989, 2016). "Currently, the association between cancer incidence and/or progression and RAD51 is strictly correlative." (PMID 27513445, 2016). "A number of studies, such as tissue expression experiments, animal models, and clinical trials suggest that RAD51 plays an important role in carcinogenesis, and numerous research groups have analyzed the link between RAD51 polymorphisms and cancer risk." (PMID 27733989, 2016). "Our results point to the mechanism underlying the effects of rs12593359 and rs11855560 on the regulation of RAD51 expression and provide an explanation for the tumor susceptibility associated with these SNPs according to cancer research." (PMID 27733989, 2016). "One particularly interesting DNA repair gene that has been associated with cancer in the context of therapeutic resistance is Rad51." (PMID 27891292, 2016). "Meanwhile, two different single-nucleotide variants affecting intron regions of RAD51 were shown to increase cancer risk in carriers of mutations in the BLM gene." (PMID 25539919, 2015). "Although RAD51 is another central component in the HR pathway, the association of RAD51 expression and cancer prognosis remains controversial." (PMID 26046797, 2015).